ALB (albumin)
Diseases named in the same sentence as ALB in open-access papers (continued):
Sharing a sentence is not in itself a finding about the gene and the disease.
chronic kidney disease (continued). "Indeed, a greater reduction in SBP was observed during the fourth week of study among these specific patient groups, i.e., older patients aged ≥ 75 years, as well as those with macro-albuminuria (urine albumin-creatinine ratio > 300 mg/g) and chronic kidney disease stage 3–4 [9••]." (PMID 37566184, 2023). "The National Kidney Foundation recently proposed a ≥ 30% decrease in urinary albumin–to–creatinine ratio (UACR) over 0.5–2 years as a surrogate endpoint for chronic kidney disease (CKD) progression in individuals with baseline UACR > 30 mg/g." (PMID 37606804, 2023). "Chronic kidney disease (CKD) can be detected early by detecting a small amount of human serum albumin (HSA) in urine or microalbuminuria (30–300 μ g/mL)." (PMID 37138743, 2023). "eGFR, estimated glomerular filtration rate; UACR, urinary albumin-creatinine ratio; CKD, chronic kidney disease; CAD, coronary artery disease; VHD, valvular heart disease." (PMID 36980454, 2023). "Albuminuria, defined as the presence of albumin in the urine (albumin excretion rate > 30 mg/d), has been highly correlated to kidney damage and is detectable in the early stages of Chronic Kidney Disease (CKD)." (PMID 37161502, 2023). "Chronic kidney disease (CKD), defined as a progressive loss of functional nephrons leading to a gradual reduction in the glomerular filtration rate (GFR) and increased urinary albumin excretion, has become a global public health problem and a recognized risk factor for cardiovascular disease (CVD)." (PMID 35204237, 2022). "Protein-energy wasting (PEW) relates to the situation in which an individual progressively loses his fat stores, muscle mass and albumin levels in the course of chronic kidney disease (CKD)." (PMID 36558477, 2022). "Oxidative stress most likely plays a significant role in the pathogenesis of sepsis, end-stage renal disease or liver failure, and it is believed albumin might improve patient outcomes by having a neutralizing effect, since cysteine-34 is a particularly redox-sensitive site of albumin." (PMID 36142472, 2022). "TOD was assessed as carotid intima-media thickness (CIMT), chronic kidney disease (CKD), urinary albumin-creatinine ratio (ACR), estimated glomerular filtration rate (eGFR) and left ventricular mass index (LVMI)." (PMID 35865385, 2022). "To date, no reports have investigated the combined predictive value of BNP and urinary albumin for long-term cardiovascular–renal events in patients with chronic kidney disease (CKD)." (PMID 37234386, 2022). "Albuminuria is a pathological condition in which there is an abnormally high concentration of albumin in urine, which is a sign of liver cirrhosis in patients with chronic hepatitis and chronic kidney disease (CKD)." (PMID 36354425, 2022). "For example, the IG technique ranked albumin, hemoglobin, packed cell volume, red blood cell count, and serum creatinine as the most informative features, and numerous studies have identified a strong correlation between these variables and chronic kidney disease." (PMID 36004875, 2022). "The secondary outcome was chronic kidney disease (CKD) development (composite of estimated glomerular filtration rate < 60 ml/min/1.73 m2 and/or random urine albumin-to-creatinine ratio ≥ 30 mg/g)." (PMID 35831434, 2022). "Accordingly, A recent meta-analysis of the Chronic Kidney Disease Prognosis Consortium (CKD-PC) showed that inclusion of combined urinary albumin-to-creatinine ratio (ACR) and eGFR improves cardiovascular risk prediction in NDD-CKD populations." (PMID 37675027, 2022). "Hyperleptinemia is associated with impaired kidney function, including increased excretion of urinary albumin and a reduced glomerular filtration rate in patients with chronic kidney diseases (CKD)." (PMID 35628271, 2022). "BMI, body mass index; SBP, systolic blood pressure; DBP, diastolic blood pressure; UALB, urine albumin; CKD, chronic kidney disease; LVH, left ventricular hypertrophy." (PMID 35911424, 2022).
chronic kidney disease (continued). "Chronic kidney disease (CKD) is defined as a relevant excretion of albumin into the urine or a reduction of the glomerular filtration rate (GFR) over a longer time period of ≥ 3 months." (PMID 36323846, 2022). "Chronic kidney disease (CKD) is an age-associated decline in renal function, diagnosed by impaired glomerular filtration rate (GFR) or increased urinary albumin excretion (albuminuria)." (PMID 34661687, 2022). "Chronic kidney disease (CKD), defined as reduced glomerular filtration rate, increased urinary albumin excretion, or both, is becoming an increasing public health issue." (PMID 33934104, 2021). "In our study, we aimed to evaluate the one-year mortality rate after dialysis induction and the impact of serum albumin levels on outcomes in patients with chronic kidney disease (CKD) and heart failure (HF)." (PMID 34640538, 2021). "Chronic kidney disease (CKD) is characterized by long-term impairment of renal function (reduced glomerular filtration rate or increased excretion of urinary albumin or both) and has become a global health issue." (PMID 34257680, 2021). "Patients with stage 3 chronic kidney disease (CKD) or positive urine microalbuminuria (urine to albumin creatinine ratio; UACR > 20–200 mg/mmol) were recruited into a randomized, double-blind, placebo-controlled trial." (PMID 33477404, 2021). "For the diagnosis of chronic kidney disease (CKD), guidelines recommend performing an initial albuminuria testing using either the albumin-to-creatinine ratio (ACR) or the protein-to-creatinine ratio (PCR)." (PMID 34765776, 2021). "In addition, hypercholesterolemia that increases urinary albumin excretion may contribute to the progression of chronic kidney disease." (PMID 34110719, 2021). "In addition to CRP, serum albumin correlates with LTM in chronic kidney disease patients." (PMID 32824951, 2020). "Meanwhile, the Chronic Kidney Disease Japan Cohort (CKD-JAC) also reported that increased albumin-to-creatinine ratio at the baseline was significantly associated to eGFR halving and progression to ESKD at the primary end-point." (PMID 32941535, 2020). "In fact, an increase in urinary albumin related to an impairment of glomerular filtration has been reported in dogs and cats with chronic kidney disease (CKD)." (PMID 32961670, 2020). "Chronic kidney disease (CKD) is defined as the glomerular filtration rate (GFR) lower than 60 ml/min per 1.73 m2 or a urinary albumin-to-creatinine ratio more than 30 mg/g." (PMID 31998731, 2019). "Chronic kidney disease (CKD) was defined as eGFR <60 mL/min/1.73 m2 or urine albumin-to-creatinine ratio >30 mg/g creatinine." (PMID 31619722, 2019). "Chronic kidney disease (CKD) is diagnosed using the estimated glomerular filtration rate (eGFR) and the urinary albumin:creatinine ratio (ACR)." (PMID 29970394, 2018). "The diagnosis of chronic kidney disease (CKD) is currently based on the estimated glomerular filtration rate (eGFR) and urinary albumin excretion." (PMID 28918021, 2017). "The current assessment of kidney health and the definition of chronic kidney disease (CKD) are limited to measures or estimates of glomerular filtration rate (eGFR) and urinary albumin-creatinine ratio (ACR)." (PMID 28332475, 2017). "This study investigated the correlation between the albumin-to-creatinine ratio in the urine and 24-hour urine proteinuria and whether the ratio can predict chronic kidney disease progression even more reliably than 24-hour proteinuria can, particularly in primary IgA nephropathy." (PMID 27276392, 2016). "Albuminuria categorization constitutes one of the chronic kidney disease (CKD) classification systems and measuring the albumin-to-creatinine ratio (ACR) in the urine has been recommended as a standard preferable to monitoring proteinuria 11,12." (PMID 27276392, 2016).
chronic kidney disease (continued). "Chronic kidney disease (CKD), which is defined by glomerular filtration rate less than 60 mL/min/1.73 m2 or albuminuria more than 30 mg per day (or urinary albumin/creatinine ratio > 30 μg/mg), has become a public health issue." (PMID 27545472, 2016). "This masking effect is also expected to be pronounced in the analysis of the urinary proteome of patients with chronic kidney disease (CKD) who present high levels of urinary albumin." (PMID 26208298, 2015). "Chronic kidney disease patients in the registry from November 2007 through November 2011 with a complete set of observations of estimated glomerular filtration rate, calcitriol, albumin, free calcium, phosphate, and parathyroid hormone were included in the study (n = 284)." (PMID 23865435, 2013). "Disease severity stratification employed two validated biomarkers: urinary albumin excretion rate (AER) and eGFR calculated using the Chronic Kidney Disease Epidemiology Collaboration equation." (PMID 40860624, 2025). "Albumin (ALB) levels were lower in HD patients (p < 0.0001), consistent with chronic inflammation and protein-energy wasting commonly observed in end-stage renal disease." (PMID 41226704, 2025). "Habitual coffee consumption was found to be inversely and dose-dependently correlated with the incidence of chronic kidney disease (CKD), end-stage kidney disease (ESKD), and albuminuria (elevated urinary albumin excretion)." (PMID 41531586, 2025). "CAVI, cardio-ankle vascular index; CI, confidence interval; CKD, chronic kidney disease; eGFR, estimated glomerular filtration rate; T2D, type 2 diabetes; UACR, urinary albumin-to-creatinine ratio." (PMID 41351003, 2025). "Kidney function outcomes included chronic kidney disease (CKD), estimated glomerular filtration rate (eGFR), and urinary albumin‐to‐creatinine ratio (UACR)." (PMID 41169788, 2025). "Diabetic nephropathy (DN) presents as chronic kidney disease (CKD), characterized by a reduced glomerular filtration rate (GFR) and elevated urinary albumin excretion due to renal damage induced by poor long-term glycemic control." (PMID 40283140, 2025). "Underweight individuals were similarly more likely to have pre-existing chronic kidney disease (CKD) (P < 0.001), lower median preprocedural albumin (P < 0.001), and lower hemoglobin levels (P < 0.001) compared to the other BMI groups." (PMID 40908085, 2025). "Therefore, the sensitivity and specificity of urinary albumin, particularly microalbuminuria, are limited, posing challenges for early diagnosis and appropriate classification of chronic kidney disease (CKD) in clinical settings." (PMID 40958907, 2025). "However, assessment of the urinary spot albumin to creatinine ratio (uACR) is often overlooked, whereas it is crucial for determination of chronic kidney disease (CKD)." (PMID 41010810, 2025). "Chronic kidney disease (CKD) is defined as eGFR <60 mL/min/1.73 m2; and/ or albuminuria, defined as an albumin:creatinine ratio ≥3.0 mg/mmol." (PMID 38402394, 2024). "Chronic kidney disease (CKD) is defined as persistently reduced estimated glomerular filtration rate (eGFR) <60 mL/min/1.73 m2, persistently elevated urine albumin excretion, or both for more than 3 months." (PMID 38398269, 2024). "The negative association of serum albumin levels with mortality in long-term follow-up has also been found in elderly people, post-surgical patients, patients after acute myocardial infarction, and patients with chronic kidney disease, which is consistent with our findings." (PMID 39026682, 2024). "Chronic kidney disease (CKD), characterised by a reduced estimated glomerular filtration rate (eGFR), increased urinary albumin excretion, or both, is acknowledged as a pressing public health issue." (PMID 38965471, 2024). "Moreover, GLP-1 receptor agonists have been linked to enhanced kidney health, characterized by decreased levels of albumin in the urine and a potential deceleration in the advancement of chronic kidney disease (CKD)." (PMID 39219906, 2024).
chronic kidney disease (continued). "Chronic Kidney Disease (CKD), characterized by a reduced glomerular filtration rate [eGFR < 60 mL/min/1.73 m2) or the presence of albuminuria (urine albumin-creatinine ratio (UACR) ≥ 30 mg/g], represents a significant and escalating global health concern." (PMID 38919480, 2024). "The urinary protein-to-creatinine ratio (PCR) and urinary albumin-to-creatinine ratio (ACR) are essential for evaluating chronic kidney disease (CKD), and the importance of assessing urinary albumin in children is now attracting more attention." (PMID 37676464, 2024). "According to the Kidney Disease Improving Global Outcomes chronic kidney disease (CKD) guideline, increased albuminuria was defined as urinary albumin‐to‐creatinine ratio (UACR) ≥30 mg/gCr, indicating kidney damage." (PMID 37986707, 2024). "We performed four sensitivity analyses after excluding patients who had receivedan albumin infusion in the 3 days prior to ICU admission, alongside patients withmalignancy, cirrhosis, and chronic kidney disease." (PMID 39077353, 2024). "Also, potential confounding factors that may affect the CAR by lowering serum albumin levels, such as the presence of underlying comorbidities like liver cirrhosis or chronic renal failure, were not assessed." (PMID 39064483, 2024). "We examined the changes in eGFR and urinary albumin creatinine ratio (ACR) values 3 years before and 3 years after their first event of hospitalization with chronic kidney disease as the primary diagnosis." (PMID 37984378, 2024). "However, the diagnosis of end stage renal disease is validated since medical reimbursement of dialysis care is applied after quarterly reporting longitudinal laboratory data (such as measurement of dialysis clearance, hemoglobin, albumin, intact-PTH data) by attending physicians." (PMID 36837885, 2023). "At least half of all adults with type 2 diabetes (T2D) have comorbid chronic kidney disease (CKD), with either an elevated urinary albumin excretion rate (uAER) and/or a reduced estimated glomerular filtration rate (eGFR)." (PMID 37159343, 2023). "The current standard of care (SoC) for monitoring chronic kidney disease (CKD) relies primarily on serial measurement of the estimated glomerular filtration rate (eGFR) and urinary albumin–creatinine ratio (uACR)." (PMID 37176686, 2023). "The DAPA-CKD (Dapagliflozin and Prevention of Adverse Outcomes in Chronic Kidney Disease) trial included 4304 individuals with an eGFR of 25 to 75 mL/min/1.73 m2 and a urinary albumin-to-creatinine ratio of 200 to 5000 mg/g." (PMID 37959263, 2023). "Approximately half of the patients with type 2 diabetes and one–third with type 1 diabetes develop chronic kidney disease (CKD), which is clinically defined by the presence of impaired renal function, elevated urinary albumin excretion, or both." (PMID 37007029, 2023). "The urine albumin creatine ratio has been widely used as a conventional biomarker for the onset of DKD and its progression to end-stage renal disease, but there are some differences between the clinical manifestations and histopathological damage of DKD." (PMID 37020588, 2023). "The presence of albumin and protein in the urine is also the most important prognostic factor for the rapid progression of CKD to end-stage renal disease (ESRD), defined by eGFR values < 15 mL/min/1.73 m2 or by the need for renal replacement therapy." (PMID 37240080, 2023). "Previous studies have reported that patients with HRS who respond to terlipressin and albumin have reduced need for RRT after LT and lower odds of developing chronic kidney disease (CKD) 1 year after LT." (PMID 38162842, 2023). "Chronic kidney disease (CKD) is defined as glomerular filtration rate (eGFR) < 60 mL/min/1.73 m2 for ≥3 months or by the presence of albuminuria, defined as albumin to creatinine ratio > 30 mg/g in two or three spot urine specimens." (PMID 37109593, 2023).
chronic kidney disease (continued). "As a result, guidelines recommend SGLT-2is as the first-line agent for type 2 diabetes (T2D) patients with established chronic kidney disease (CKD), defined as a sustained reduction in eGFR < 60 mL/min or urine albumin creatinine ratio (UACR) ≥ 200 mg/g." (PMID 37892600, 2023). "Changes in urinary albumin:creatinine ratio (UACR), as well as estimated glomerular filtration rate (eGFR), are commonly used as surrogate endpoints in chronic kidney disease (CKD) clinical trials and recognized as important risk factors for cardiovascular disease." (PMID 35041708, 2022). "Serum albumin level correlates to nutrition and inflammation status and is a well-known predictor of long-term outcomes among individuals with chronic kidney disease (CKD)." (PMID 36346823, 2022). "As with many other chronic kidney diseases (CKD), the diagnosis of DKD hinges on changes in urinary albumin excretion rate (AER) and glomerular filtration rate (GFR)." (PMID 34913986, 2022). "Chronic kidney disease (CKD) is a common worldwide health problem defined by low estimated glomerular filtration rate (eGFR) and/or elevated urine albumin to creatinine ratio (uACR)." (PMID 34413458, 2022). "Chronic kidney disease (CKD), defined as an estimated glomerular filtration rate (eGFR) less than 60 ml/min/1.73 m2 and/or a urinary albumin to creatinine ratio (ACR) greater than or equal to 30 mg/g, is a major public health problem." (PMID 36224528, 2022). "The diabetic group had a significantly higher prevalence of chronic kidney disease; higher serum HbA1c, GDF15, and urine albumin/creatine ratio." (PMID 35683420, 2022). "CD36 is expressed in tubular epithelial cells and it affects kidney lipid metabolism as well as the binding and uptake of albumin in the proximal tubule, is significantly upregulated in chronic kidney disease (CKD), and it plays a significant role both in the diagnosis and therapy of renal fibrosis." (PMID 35713363, 2022). "Classification of chronic kidney disease (CKD) and evaluation of prognosis is based on two components: estimated glomerular filtration rate (eGFR) and urinary albumin-to-creatinine ratio (ACR)." (PMID 35284809, 2022). "Chronic kidney disease (CKD) is a chronic complication of diabetes, characterized by the presence of pathological quantities of urine albumin excretion and/or accompanied by a gradual deterioration in the glomerular filtration rate (GFR)." (PMID 34975301, 2022). "Clinically, DKD is defined as the presence of persistently increased urinary albumin (>300 mg/day) or urinary albumin-to-creatinine ratio (UACR>30 mg/g), accompanied by declined kidney function, eventually to end-stage renal disease (ESRD)." (PMID 36408255, 2022). "Our retrospective survey also revealed the improvement in the urine albumin-to-creatinine ratio (ACR) in Japanese patients with type 2 diabetes mellitus (T2DM) and chronic kidney disease (CKD) in clinical practice." (PMID 35028319, 2021). "In the medical diagnosis of chronic kidney disease, two medical tests are used to detect CKD, which are by a blood test to check the glomerular filtrate or by a urine test to check albumin." (PMID 34211680, 2021). "Relationship between baseline glomerular filtration rate stratified by chronic kidney disease (CKD) stage and urinary retinol binding protein 4/creatinine ratio (uRBPCR), urinary protein creatinine ratio (uPCR), urinary albumin/creatinine ratio (uACR) and fractional excretion of phosphate." (PMID 34374069, 2021). "Chronic kidney disease (CKD) has been defined by a reduced glomerular filtration rate and increased urinary albumin excretion for three months or longer." (PMID 34067472, 2021). "Chronic kidney disease (CKD), clinically characterized by impaired renal function or elevated urinary excretion of albumin or both, affects approximately half of all patients with T2DM." (PMID 34513443, 2021).